TUG1 (taurine up-regulated 1)
Diseases named in the same sentence as TUG1 in open-access papers (continued):
Sharing a sentence is not in itself a finding about the gene and the disease.
cancer (continued). "It is necessary to systematically explore the relationship between TUG1 expression and cancer." (PMID 29029461, 2017). "TUG1 is cancer-related, binds to PRC1 or PRC2, and suppresses gene expression." (PMID 28872613, 2017). "Taurine-upregulated gene-1 (TUG1) negatively regulates miR-9 in a human cancer cell line." (PMID 28866639, 2017). "We found that HOTAIR, H19 and TUG1 almost appeared in all cancer types." (PMID 28076842, 2017). "All these studies revealed that TUG1 could function as an oncogene or tumor suppressor in different cancers." (PMID 28376901, 2017). "Accumulating evidence shows that TUG1 plays an important role in several types of cancer." (PMID 29657297, 2017). "A research demonstrated the oncogenic role and association with worse overall survival of this lncRNA, especially in high-grade muscle-invasive BC: in this study, TUG1 silencing in vitro led to 34% decrease in cancer cell proliferation and 23% reduction in the migration capacity of cancer cells." (PMID 29165379, 2017). "Recent papers have reviewed TUG1 expression in different kinds of cancer." (PMID 29657297, 2017). "LncRNA taurine upregulated gene 1 (TUG1) is reportedly dysregulated in various cancers." (PMID 28977959, 2017). "TUG1 has been identified as a tumor suppressor or oncogene in various cancer types." (PMID 28872613, 2017). "When grouped according to the expression level of TUG1 in cancer patients, the pooled HRs for the increased TUG1 expression subgroup and decreased TUG1 expression subgroup were 1.91(95% CI: 1.33–2.75, P < 0.001)) and 0.63 (95% CI: 0.48–0.82, P = 0.001 with less heterogeneity), respectively." (PMID 29029461, 2017). "Additionally, the results demonstrated that a high expression of TUG1 significantly predicted a higher tendency to develop DM in patients with cancer." (PMID 28977959, 2017). "Recent evidence demonstrated that TUG1 has pro-tumorigenic actions in several cancer types." (PMID 29371936, 2017). "LncRNA TUG1 has been demonstrated to be aberrantly expressed in several types of cancer and maybe serve as a prognostic marker for cancer patients." (PMID 28548946, 2017). "TUG1 expression may thus serve as a promising biomarker for predicting prognosis in cancer patients." (PMID 28977959, 2017). "Firstly, the co-expression patterns (log2-scale) between TUG1 and β-catenin (CTNNB1) in TCGA Pan-Cancer (PANCAN) showed that the expression of TUG1 was positively related to the expression of β-catenin, with a Pearson coefficient r = 0.1137 and P = 0.0189 (two tail, t-test) in 426 BUC samples." (PMID 29179467, 2017). "The role of Tug1 in cancer however, seems to be different in differentcellular contexts." (PMID 27508057, 2016). "Although TUG1 is recognized as the highly conserved nuclear lncRNA and is a predictive marker for metastasis development in human cancer, its role in CRC metastasis remains unclear." (PMID 26856330, 2016). "Another lncRNA deregulated in cancer is the taurine upregulated gene 1 (TUG1)." (PMID 27177333, 2016). "Among these, LincRNA taurine up-regulated gene 1 (TUG1; also known as TI-227H; Linc00080; ncRNA00080) was originally identified as a transcript up-regulated by taurine and is found to be expressed in various human cancer cell lines and tumors." (PMID 26856330, 2016). "A mount of studies showed that TUG1 promoted cancer cell invasion and radioresistance via EMT." (PMID 27421138, 2016). "In previous studies, TUG1 dysregulation has been reported in many other cancers." (PMID 27362796, 2016). "TUG1, which is such a hub lncRNAs, is identified as hub node in 11 cancer ceRNA networks." (PMID 27580177, 2016). "It is reported that TUG1 overexpression was related to cell proliferation of various cancer." (PMID 27421138, 2016). "Knockdown of Tug1 also seems to inhibit cancer cell proliferationas well as migration." (PMID 27508057, 2016).
cancer (continued). "As is known, lncRNAs involved in cancer cells biological function, and we found that knockdown of TUG1 could impair HCC cells proliferation, invasion and induce cell apoptosis both in vitro and vivo." (PMID 26336870, 2015). "Our results suggested that lncRNA, especially TUG1, may influence the same cell biological function via regulating different target genes depending on different cancer cells." (PMID 26336870, 2015). "Marvelously, PUM2 and TUG1 involved with cell cycle regulation showed significant positive expression correlation (p < 0.05) in all 14 cancer types." (PMID 25642422, 2014). "TUG1, NEAT1,HOTAIR, and CCAT1are examples of lncRNAs that might potentially cause cancer." (PMID 39512820, 2024). "Therefore, the role of TUG1 in cancer progression is still controversial." (PMID 37813900, 2023). "In contrast, depletion of TUG1 minimally affected both cell proliferation and apoptosis in normal cells, supporting the idea that TUG1 is a pivotal molecule to regulate R-loop resolution and maintain cancer cell proliferation, as we hypothesized." (PMID 37607907, 2023). "In addition, knocking down TUG1 expression could reduce PD-L1 expression and enhance the cancer cell-killing capability of T cells." (PMID 37813900, 2023). "Furthermore, our results showed that silencing TUG1 expression could partially improve effector T cell-induced killing of cancer cells." (PMID 37813900, 2023). "LncRNA TUG1, which we previously noted increases the expression of Nrf2, has also been shown to be positively regulated by Nrf2 in urothelial carcinoma of the bladder cells, thus completing a possible positive feedback loop that sustains the antioxidant response of cancer cells." (PMID 36077530, 2022). "Nevertheless, the mechanism by which TERT and TUG1 maintain dual localization in the nucleus and cytoplasm remains unknown, but could potentially provide important insights into their biology and targeting in cancer." (PMID 34083519, 2021). "In detail, in contrast to responders to platinum-based chemotherapy, lower expression of TUG1 determined in cancer tissues obtained from non-responders may be associated with poor overall survival." (PMID 31532756, 2019). "Moreover, lncRNA TUG1 is involved in the regulation of cancer progression." (PMID 31217907, 2019). "Thus, targeting the TUG1-miRNA132-Hh pathway could be a new strategy for the clinical treatment of human cancers." (PMID 29899399, 2018). "Recently, more and more scientists have found that TUG1 might play important roles in cancer proliferation and metastasis, and TUG1 expression may have a relationship with prognosis and metastasis of human cancers." (PMID 28977959, 2017). "Therefore, we performed this meta-analysis to investigate whether TUG1 could serve as a molecular marker for prognosis prediction in human cancers." (PMID 28977959, 2017). "Thus, we found that TUG1 was an independent factor of OS among patients with cancer." (PMID 28977959, 2017). "We found that high TUG1 expression may indicate a worse prognosis in cancer patients." (PMID 28977959, 2017). "Thus to date, the true function of lncRNA TUG1 in cancers was controversial." (PMID 29245996, 2017). "Notably, TUG1 expression promoted cancer cell invasion and radioresistance via triggering EMT." (PMID 28872613, 2017). "This suggests TUG1 expression could serve as a biomarker for poor prognosis in cancers." (PMID 28977959, 2017). "The overall results suggest lncRNA TUG1 may be a useful prognostic biomarker in cancer patients." (PMID 29029461, 2017). "Therefore, TUG1 may be involved in the chemotherapy and radiotherapy resistance in cancers, providing a theoretical foundation for the clinical application of TUG1 in patients with radio- and chemo-resistant cancer." (PMID 28376901, 2017). "We found that TUG1 may competitively regulate different cancer hallmarks in various cancer types." (PMID 27580177, 2016).
cancer (continued). "Our previous study was the first to demonstrate that under replication stress, TUG1 is rapidly upregulated via ATR-CHK1 signalling and interacts with DHX9, playing a crucial role in resolving R-loops formed at replication forks in cancers." (PMID 40654306, 2025). "Given our prior demonstration of the essential roles of TUG1 in cancer cells, applying CARPID to cancer cell models will enable characterization of the dynamic TUG1 interactome under cancer-specific replication stress." (PMID 40654306, 2025). "A qRT-PCR analysis of the expression of 17 lncRNAs in the serum exosomes of cancer subjects demonstrated a downregulation of lncRNA UCA1 in exosomes from the serum samples of patients, while lncRNA TUG1 was overexpressed." (PMID 37569782, 2023). "TUG-1 downregulation can be used as a distinguishing feature of cancer therapy, because TMX medication was shown to reduce TUG-1 expression." (PMID 37646973, 2023). "Here, The expression of TUG1 and PD-L1 in HCC tissues was evaluated through analysis of databases and verified in HCC tissue and HCC cancer cells by qRT-PCR." (PMID 37813900, 2023). "In the current study, we aimed to identify the role of taurine upregulated gene 1 (TUG1) and investigated its ability to cope with R-loops in cancer cells." (PMID 37607907, 2023). "Current findings regarding TUG1 not only promote a better understanding of CRC pathogenesis and development but also facilitated the progress of cancer lncRNA therapy." (PMID 36333703, 2022). "After the CD133+/CD44+ cells with cancer stem cell (CSC) characteristics were isolated and identified by flow cytometry, lncRNA TUG1 expression was quantified by quantitative real-time PCR." (PMID 34858502, 2021). "Although the cancer-promoting function of lncRNA TUG1 has been well established in CRC, there are few studies on the lncRNA TUG1 function in the characteristics and chemoresistance of CRC stem cells." (PMID 34858502, 2021). "Thirty-five cancer-relevant lncRNAs were identified, including the oncogenic lncRNAs MALAT1 and UCA1 and lncRNAs GAS5 and TUG1, which act as tumor suppressors." (PMID 33519750, 2020). "Current evidence confirms that lncRNA TUG1 has an obvious and close relationship with FMRP for patients suffering from cancer." (PMID 31191598, 2019). "Several researches have showed that the increased expression of 6 lncRNAs (H19, UCA1, TUG1, MALAT1, SPRY4-IT1, and HOTAIR) was correlated to poor prognostic outcome of cancers, those findings in consist with our results." (PMID 29870555, 2018). "Through searching the published literatures, six lncRNAs (ZFAS1, PRNCR1, GAS5, TUG1, linc-ROR, H19) which have been reported to be abnormally expressed in cancer were included in the present study." (PMID 29559565, 2018). "Several lncRNAs have been confirmed to play an important role in various types of malignant tumors, including PANDAR, ZFAS1, HOTAIR, TUG1 and so on23–26." (PMID 30111807, 2018). "Here we selected six candidate cancer-related lncRNAs (ZFAS1, PRNCR1, GAS5, TUG1, linc-ROR, and H19) through articles that were previously reported to be dysregulated in cancer." (PMID 29559565, 2018). "Among these, XIST, CDKN2B-AS1, CRNDE, TUG1, SOX2-OT, etc. have been reported playing crucial roles in inflammation pathway of cancer progression." (PMID 27809873, 2016). "In addition, some non-coding RNAs, such as LINC01087 56, TUG1 27, NEAT1 57 and circ_0020123 58, were verified to target miR-384 in cancer progression." (PMID 39132166, 2024). "The high clonogenic activity of HAN-1 cells can be related to increased expression of several long non-coding RNAs, such as TUG1, MEG3, MALAT1, NEAT1, and DANCR – all considered as modulators of stemness of cancer cells, their differentiation potential and chemoresistance." (PMID 38342891, 2024).
cancer (continued). "Knockdown of TUG1 not only inhibits CRC migration and invasion through the miR-542-3p/TRIB2 axis but also, by overexpressing it, regulates the miR-26a-5p/MMP14/p38 MAPK/Hsp27 axis in vitro and in vivo to accelerate cancer invasion." (PMID 39026978, 2024). "In addition, TUG1, a lncRNA that is overexpressed in bladder cancer tissues and cell lines, promotes EMT and decreases cancer cell sensitivity to ionizing radiation through the miR-145/ZEB2 axis." (PMID 36605618, 2023). "TUG1 and LINC00657 are frequently studied lncRNAs in various cancers, except PCa." (PMID 37754243, 2023). "After treatment with TUG1 ASO for 24 h, FCM showed significant decrease in DNA replication rate (i.e. EdU incorporation) and increased numbers of γ-H2AX-positive cells in the S phase of HeLa/Fucci2 and other cancer cell lines." (PMID 37607907, 2023). "We provide a new paradigm whereby targeting TUG1 by ASO, coupled with DNA-damaging agents, may be an effective novel strategy for the treatment of cancers, particularly those with a high RS and R-loop burden." (PMID 37607907, 2023). "Another study revealed TUG1 silencing increased radiosensitivity in a xenograft model by inhibiting expression of HMGB1, a conserved nuclear protein that promotes metastasis in various cancers." (PMID 36605618, 2023). "TUG1, aberrantly expressed in CRC, takes part in the cancer’s progression." (PMID 35014946, 2022). "We focused on two cancer-related transcripts, TERT mRNA and TUG1 lncRNA." (PMID 34083519, 2021). "Although lncRNA TUG1 has been well studied in many human cancers, its role in IH progression has not been explored." (PMID 34362467, 2021). "Without affecting cell cycle distribution and apoptosis, TUG1 knockout reduces the ability of proliferation and migration of cancer cells." (PMID 34026626, 2021). "We found four paired lncRNA-mRNA exhibiting a substantially high SCNA frequency in cancers, including lncRNA FGD5-AS1 and PRKAR2A (KIRC, 44.2% and 44.4%), lncRNA TUG1 and CDC7 (LUAD, 25.9% and 23.6%), lncRNA TUG1 and DSC2 (LUAD, 25.9% and 26.1%) and lncRNA SNHG7 and PNMA2 (LUAD, 25.4% and 31.1%)." (PMID 32846981, 2020). "In this study, by integrating the expression profiles of the GEO datasets GSE45827 and GSE65216, we identified hundreds of differentially expressed lncRNAs, including HOTAIR, ASAP1-IT1, TUG1, and MIAT, which have been reported to be related to cancer by other investigators." (PMID 32352014, 2020). "We found lower expression of TUG1 in cancer tissues obtained non-responders to platinum-based chemotherapy in contrast to responders and reflected poor overall survival." (PMID 31532756, 2019). "For example, the lncRNAs TUG1, UCA1, SPRY4-IT1, HULC, HOTTIP, H19 and HOTAIR were found to be novel promising biomarkers for poor prognosis in human cancers." (PMID 29308050, 2018). "The abundance of the selected mRNAs with various expression levels, as well as enhancer-associated RNAs and cancer biomarker long non-coding RNAs (MALAT1, GAS5 and TUG1), were not significantly different between the two groups as assessed by RT-qPCR." (PMID 30140372, 2018). "We found modest, but not consistently statistically significant increases of TUG1 in cancer tissues across both tissue sets." (PMID 28430799, 2017). "In conclusion, the current meta-analysis demonstrated that TUG1, SPRY4-IT1, and HULC might serve as a moderate predictor of survival in human cancer." (PMID 29145271, 2017). "As emerging stars in cancer biomarkers, more and more lncRNAs were identified, and some functioned as oncogenes, such as CCAT2, HOTTIP and TUG1, while some may be acted as tumor suppressor genes, such as MEG3, GAS5, ANRIL." (PMID 28977885, 2017). "To examine how miRNAs mediate these conserved ceRNA pairs in pan-cancers and to gain insight into the commonalities of various cancers, we focused on two ceRNA pairs: OIP5-AS1-BRCA1 and TUG1-TGFBR2, both of these two mRNAs are cancer driver genes and lncRNAs with highly degree in the subnetwork." (PMID 27580177, 2016).
cancer (continued). "Taken together, Tug1 enhances the recruitment of Ybx1 to the promoter regions of Pdl1 and Cd47 to promote their expression, and then inhibits the function of CD8+ T cell and the phagocytosis function of macrophages toward cancer cells, thereby regulating the antitumor immune response." (PMID 38981064, 2024). "In the current study, in addition to fundamental expression control of TUG1 by MYC, we found the ATR-CHK1-E2F pathway directly upregulated TUG1 expression in response to HU and CPT exposure (i.e. two hours of treatment), which induced more abundant RS and R-loop, in cancer cells." (PMID 37607907, 2023). "Although the underlying mechanisms responsible for the preferential engagement of TUG1-RPA-DHX9 for R-loop resolution at CA microsatellite regions remain to be elucidated, our data indicate that TUG1 is involved in resolution of R-loops at specific loci in cancer cells." (PMID 37607907, 2023). "The nuclear localization and intron retention observed in healthy iPS cells that endogenously express TUG1 and TERT led us to explore whether this phenomenon also occurs in other cell types and contexts such as cancer, where TERT expression is reactivated and TUG1 is expressed." (PMID 34083519, 2021). "The pooled results suggested that overexpression of TUG1 was significantly correlated with unfavorable overall survival (OS) (HR = 1.70, p < 0.001), shorter recurrence-free survival (RFS) (HR = 2.40, p ≤ 0.001), and shorter event-free survival (EFS) (HR = 1.88, p < 0.001) in patients with cancer." (PMID 33747256, 2021). "We showed that TUG1 may regulates the proliferation ability of HCC cells partially through sliencing of the KLF2 by binding with PRC2, which suggested that lncRNAs contribute to different cancer cells biological function through regulating different genes." (PMID 26336870, 2015). "TUG1 is overexpressed and oncogenic in many, though not all, cancers, but its potential actions through IGF-2 upregulation have not been explored in a cancer context." (PMID 35597813, 2022).
kidney diseases (6 papers, 2020 to 2025). "Accumulating evidence shows that TUG1 plays a therapeutic role in many human kidney diseases, especially in the field of mitochondrial bioenergetics in DN." (PMID 40685567, 2025). "TUG1 plays important roles in many human kidney diseases, such as DN, acute kidney injury, lupus nephritis, interstitial fibrosis, and renal cell carcinoma." (PMID 40685567, 2025). "Among all lncRNAs related to kidney disease, TUG1 is of particular interest." (PMID 40685567, 2025). "PGC-1α regulation may also involve the long-coding mRNA Tug1, with studies suggesting that increased Tug1 levels may restore PGC-1α levels in kidney disease." (PMID 39597916, 2024). "In addition, it is noteworthy that by analyzing lncRNA studies performed on renal diseases, we can identify six lncRNAs involved in more than one type of renal disease, in particular PVT1, TUG1, NEAT1, MALAT1, XIST, and H19." (PMID 37190024, 2023).
cardiac disease (4 papers, 2019 to 2022). "Taurine upregulated gene 1 (TUG1), an evolutionarily conserved lncRNA, has been recently reported to be linked to several heart diseases." (PMID 34540908, 2021). "Several studies showed that TUG1 is involved in the process of adverse responses to cardiac disease." (PMID 32565910, 2020). "The lncRNA databases also recommend other heart disease-related lncRNAs, which were differentially expressed in particular ANT-treated conditions, including MALAT1, MEG3, TUG1, GAS5, CASC1S." (PMID 35415316, 2022).
cardiovascular diseases (4 papers, 2021 to 2025). "Multiple studies have confirmed that the abnormal expression of lncRNA TUG1 is closely related to the disease progression of various conditions, particularly cardiovascular diseases." (PMID 39967688, 2025). "The lncRNA taurine-up regulated gene 1 (TUG1), significantly contributes to cardiovascular diseases; however, its contribution to CME-induced myocardial damage remains elusive." (PMID 34163467, 2021).